NLRP3 (NLR family pyrin domain containing 3)
Diseases named in the same sentence as NLRP3 in open-access papers (continued):
Sharing a sentence is not in itself a finding about the gene and the disease.
atherosclerosis (continued). "For example, NLRP3 overexpression is associated with high levels of oxidized low-density lipoprotein (oxLDL) in plasma from OSA patients with early subclinical atherosclerosis, indicating an interaction between dyslipidemia and inflammation in inducing tissue injury." (PMID 38339130, 2024). "Furthermore, NLRP3 activation is associated with atherosclerosis, neuroinflammation, gout, and hemorrhagic stroke." (PMID 39707045, 2024). "The NLRP3 inflammasome plays an important role in innate immune-mediated inflammation, and its aberrant activation is closely associated with several human diseases, such as gout, atherosclerosis, as well as inflammatory bowel diseases." (PMID 39701924, 2024). "We plausibly speculate that salidroside might ameliorate atherosclerosis by inhibiting the NLRP3-associated gut-coronary axis." (PMID 39092226, 2024). "In terms of pathophysiology, the over-activation of the NLRP3 inflammasome in vascular cells has been tightly associated with vascular diseases, such as atherosclerosis, stroke or hypertension, and, more recently, with COVID-19-associated vasculopathy and hyperinflammation." (PMID 38225643, 2024). "Given that the abnormal activation of NLRP3 has been linked to various diseases, including neutrophilic asthma, Alzheimer’s disease, inflammatory bowel disease, and atherosclerosis, biopharmaceutical companies are now developing NLRP3 inhibitors as potential treatments for these conditions." (PMID 39201704, 2024). "This study confirms that the regulatory effect of VRAC on the NLRP3 inflammasome may facilitate the establishment of a novel research field for understanding the pathogenesis of Alzheimer's disease, atherosclerosis, and other NLRP3-associated diseases." (PMID 39113714, 2024). "Quantitative trait locus mapping and molecular technologies in mice have identified new genetic loci (Ath28, Ath22, Ath26) and associated genes (Soat1, Gpnmb, AKR Pycard) associated with NLRP3 inflammasomes that determine macrophage phenotypes and associated atherosclerosis plaque and pathology." (PMID 38275616, 2024). "We propose that, in chronic atherogenic conditions, heightened NLRP3 activation in hematopoietic cells may promote the atherosclerosis development associated with GD." (PMID 37988162, 2024). "Furthermore, the NLRP3 inflammasome, a protein complex associated with the inflammatory progression of atherosclerosis, has attracted much interest in the pathogenesis of atherosclerosis." (PMID 38025082, 2023). "Interestingly, NLRP3 activation has been found to be especially strong in OSA patients with early subclinical atherosclerosis (eSA) providing a possible mechanism for OSA-associated atherosclerotic risk." (PMID 37175608, 2023). "Other mechanisms of NLRP3 activation have been implicated in atherosclerosis." (PMID 37443800, 2023). "In addition to its role in IR and AT inflammation, activation of the NLRP3 inflammasome has also been implicated in the development and progression of atherosclerosis, a chronic inflammatory disease of the arterial walls." (PMID 37239938, 2023). "Notably, patients with RA are at an increased risk of premature death due to accelerated atherosclerosis in cardiovascular comorbidities, while NLRP3 inflammasome activation and production of IL-1β, TNF-α, and IL-6 are also key immune mediators of RA." (PMID 37720032, 2023). "Interestingly, NLRP3-dependent TF-release has been associated with several cardiovascular diseases including hypertension, ischemic cardiomyopathy, atherosclerosis, acute myocardial infarction, and acute coronary syndromes." (PMID 35819747, 2023).
atherosclerosis (continued). "From the presented literature, it is evident that dyslipidemia, a major risk factor for atherosclerosis, triggers inflammasome activation, particularly the NLRP3 inflammasome, through the recognition of lipid-related stimuli such as oxidized LDL and cholesterol crystals." (PMID 37765019, 2023). "Cholesterol crystals are primarily implicated in triggering NLRP3 activation in atherosclerosis." (PMID 37762961, 2023). "Our results showed that WHB could attenuate atherosclerosis, which might be associated with the improvement of the NLRP3 inflammasome pathway and gut microbiota." (PMID 37836470, 2023). "Furthermore, smoking and hypertension, significant risk factors for atherosclerosis, have been also identified as NLRP3 activators." (PMID 36768920, 2023). "Numerous studies show that activated NLRP3 inflammasomes are tightly associated with many chronic inflammatory and metabolic diseases, such as ischemic heart diseases and diabetes mellitus, stroke, atherosclerosis, and hypertension." (PMID 36703963, 2022). "As an essential component of host defense, however, the dysregulated NLRP3 inflammasome activity causes uncontrolled inflammation, which underlies multiple diseases, such as gout, type 2 diabetes, atherosclerosis, and idiosyncratic drug-induced liver injury (IDILI)." (PMID 35810159, 2022). "Also, when atherosclerosis is caused by diabetes, traditional Chinese medicine works well to control the NLRP3 inflammatory response." (PMID 36532728, 2022). "Thus, through NLRP3 inflammasome, Btk is closely linked to atherosclerosis, cardiac dysfunction associated with sepsis, and atrial fibrillation." (PMID 35296647, 2022). "Moreover, impaired atherosclerosis progression and stabilization of atherosclerotic plaque were observed due to NLRP3 deficiency." (PMID 35493086, 2022). "Previous studies have demonstrated that ROS can activate NLRP3 inflammasomes and then cause cellular damage by inducing caspase-1 activation and IL-1β secretion in the development of atherosclerosis, and IL-1β has been noted as the most important pro-inflammatory cytokine in IVD degeneration." (PMID 35887297, 2022). "This study revealed that BJJ could inhibit NLRP3 inflammasome and alleviate diabetes-associated atherosclerosis." (PMID 35692570, 2022). "NLRP3 inflammasome is a key component of the innate immune system, and abnormal activation of the NLRP3 inflammasome has been implicated in various inflammatory diseases, including Alzheimer’s disease, diabetes, atherosclerosis, acute pancreatitis, fibromyalgia, etc.." (PMID 35887297, 2022). "The difference in aortic plaque size between the Tet2-deficient mice and control mice was abrogated by use of an NLRP3 inhibitor, identifying a key role for NLRP3-mediated IL-1β overproduction in promoting atherosclerosis in those harboring TET2 CHIP mutations." (PMID 35122117, 2022). "Furthermore, the over-activation of NLRP3 has been associated with several chronic diseases such as Alzheimer’s disease, diabetes mellitus, atherosclerosis, and arthritis." (PMID 35390035, 2022). "The activation of nucleotide-binding and leucine-rich repeat immune receptor (NLR) family pyrin domain containing 3 (NLRP3) inflammasome mediating interleukin- (IL-) 1β secretion has recently emerged as an important component of inflammatory processes underlying atherosclerosis." (PMID 35464766, 2022). "However, current studies have shown that the abnormal activation of the NLRP3 inflammasome is associated with inflammatory diseases such as atherosclerosis, diabetes, and pneumonia." (PMID 35418866, 2022). "However, little is known about the molecular mechanism underlying how NLRP3 inflammasome impacts atherosclerosis." (PMID 36304814, 2022). "Recently, it was reported that NLRP3 inflammasome inhibition could be one of the mechanisms underlying metformin’s effects to inhibit diabetes-accelerated atherosclerosis." (PMID 35754962, 2022).
atherosclerosis (continued). "In addition, in ApoE–/– mice treated with the selective NLRP3 inhibitor MCC950 or silencing Nlrp3 by lentivirus, atherosclerosis progression was reduced, confirming NLRP3 inflammasome as a causative factor." (PMID 36082127, 2022). "Anomalous NLRP3 inflammasome activation is linked to the development of many diseases, including cryopyrin-associated periodic syndromes, sepsis, gout, osteoarthritis, Alzheimer's disease, diabetes, atherosclerosis, steatohepatitis, and colitis." (PMID 34692754, 2021). "Importantly, overabundance of NETs (NETosis) and dysregulation in NLRP3 inflammasome activation have both been associated with similar disease phenotypes—namely, atherosclerosis, ischemia-reperfusion injury and hypoxia-induced venous thromboembolism." (PMID 34639062, 2021). "Furthermore, the activation of NLRP3 is also associated with the pathogenesis of cardiovascular diseases including atherosclerosis, hypertension, infectious cardiac diseases, and heart failures." (PMID 33613822, 2021). "In fact, it has been demonstrated that some mitochondrial mutations may lead to chronic inflammatory processes associated with NLRP3 activation, a key pathogenic factor in atherosclerosis development." (PMID 33807807, 2021). "Since aberrant activation of NLRP3-inflammasome and IL-1 are associated with numerous chronic diseases, including cardiovascular, atherosclerosis and diabetes, the interest in developing or identifying potent and specific NRLP3 inhibitors has been of increased interest." (PMID 33923693, 2021). "NLRP3 inflammasome activation has been implicated in the initiation or development of different inflammatory diseases such as gout, myocardial infarction, and diabetes, obesity, glomerular injury, and atherosclerosis." (PMID 33409276, 2020). "In addition, a variety of inflammatory diseases, including Parkinson’s disease, Alzheimer’s disease, inflammatory bowel disease, and atherosclerosis, are associated with the NLRP3 inflammasome." (PMID 33182702, 2020). "In addition, NLRP3 has been associated with gout, type 2 diabetes, multiple sclerosis, atherosclerosis, and Alzheimer's, Parkinson's, and prion diseases." (PMID 33101293, 2020). "It has been clearly shown that, in the atherosclerotic plaque, endocytosed LDL release cholesterol that upon crystallization may activate the NLRP3 inflammasome, resulting in the release of mature IL-1β and IL-18, associated with augmented atherosclerosis." (PMID 32585928, 2020). "Furthermore, if there indeed is increased inflammasome activation in diabetes, this can result in pyroptosis, an inflammatory type of cell death linked to the NLRP3 inflammasome that has been proposed to play a role in atherosclerosis." (PMID 32118048, 2020). "Many endogenous danger signals are present in radiation-induced atherosclerosis, which indicates that the NLRP3 inflammasome may be linked to metabolic disturbances, irradiation damage, and inflammation." (PMID 32226786, 2020). "Increased levels of AdipoR2 were observed in old WT mice when compared with NLRP3−/−, which could be associated with AdipoR2 deficiency‐dependent protection of atherosclerosis." (PMID 31625260, 2020). "NLRP3 is closely associated with the formation of atherosclerosis." (PMID 31487691, 2019). "Because both NLRP3 and caspase-1 deficiency decreases atherosclerosis in ApoE-/- mice, therapeutic modulation of NLRP3 or caspase-1 activity is likely to offer significant health benefits for patients with severe atherosclerosis." (PMID 31019462, 2019).
atherosclerosis (continued). "Moreover, recent studies showed that accumulation of free cholesterol in macrophages leading to activation of NLRP3 inflammasome and production of interleukin-1β (IL-1β) has been linked to atherosclerosis-associated inflammation." (PMID 30983887, 2019). "Gene silencing of NLRP3 suppresses atherosclerosis and stabilizes plaques in ApoE-deficient mice." (PMID 31582899, 2019). "In the context of AGEs activation of the NLRP3 inflammasome, there are reports that AGEs may serve as a pathogenic factor to activate NLRP3 or other inflammasome under different pathological conditions such as aging, DM, atherosclerosis." (PMID 31737627, 2019). "In addition, miR-30c-5p was linked to an indirect regulation of NLRP3 expression in atherosclerosis." (PMID 31118894, 2019). "Hence, pyroptosis is likely a cellular mechanism underlying the detrimental effect of nicotine on atherosclerosis with the production of ROS and activation of NLRP3 as the upstream mediators." (PMID 29416034, 2018). "The NLRP3 (nucleotide-binding domain and leucine-rich repeat pyrin domain containing 3) inflammasome-mediated inflammatory responses are critically involved in the progression of atherosclerosis (AS), which is the essential cause for cardiovascular diseases." (PMID 30254716, 2018). "As aberrant NLRP3 activation has also been implicated in more complex diseases including type 2 diabetes, gout, atherosclerosis and neurological diseases, scutellarin may have potential application in the treatment of such disorders." (PMID 29375379, 2017). "Indeed, recent studies reported that the deficiency of NLRP3 inflammasome components prevents the atherosclerosis progression." (PMID 29259717, 2017). "Although chronic inflammation and NLRP3 inflammasome activation have been implicated in atherosclerosis and fatty liver disease, whether SREBP-1c is involved in regulating NLRP3 and IL-1β expression in HGFs remains largely unknown." (PMID 28083517, 2016). "Notably, the activation of the NLRP3 inflammasome has been recently implicated also in the pathogenesis of atherosclerosis." (PMID 24244322, 2013). "Future studies should investigate whether the lack of inflammasome activation is a reason why female mice are protected against severe systemic and metabolic comorbidities, as previous studies linked NLRP3 activation with insulin resistance and atherosclerosis." (PMID 39696610, 2024). "Scropolioside B, isolated from a Tibetan medicine, Scrophularia dentada Royle ex Benth., could inhibit NF-κB activity, reduce NLRP3 expression, and suppress the maturation and release of IL-1β, suggesting its therapeutic potential in RA and its associated atherosclerosis." (PMID 38203796, 2024). "Thus, NLRP3 inflammasome may amplify the inflammation associated with COVID-19, potentially accelerating the progression of atherosclerosis." (PMID 39113913, 2024). "Furthermore, we describe the specific molecular mechanism underlying the PCSK9 and NLRP3 inflammasome signaling pathway in atherosclerosis and cells related to inflammation, including vascular smooth muscle cells (VSMCs), endothelial cells (ECs) and macrophages (MФ)." (PMID 36911736, 2023). "However, the aberrant activation of the NLRP3 inflammasome has been linked to several inflammatory disorders, which include cryopyrin-associated periodic syndromes, Alzheimer’s disease, diabetes, and atherosclerosis." (PMID 36881352, 2023).
atherosclerosis (continued). "Inhibitors targeting inflammasome components, including NLRP3, have shown promise in preclinical studies and may represent a new class of anti-inflammatory agents capable of disrupting the inflammatory cascade underlying atherosclerosis." (PMID 37765019, 2023). "The activation of the NLRP3 inflammasome plays a critical role in the regulation of host immune responses and is closely linked to the pathogenesis of inflammatory diseases such as autoinflammatory diseases, atherosclerosis, non-alcoholic fatty liver disease, diabetes, and gout." (PMID 33670601, 2021). "Furthermore, the NOD like receptor family pyrin domain containing 3 (NLRP3) inflammasome, discussed in greater detail below as a therapeutic target for inflammation resolution in atherosclerosis, induces a loss of barrier in the diabetic vascular environment (Li X.-X." (PMID 35002720, 2021). "However, whether the miR‐302/367 cluster was involved in atherosclerosis by regulating the NLRP3 inflammasome and its underlying mechanisms remained unclear." (PMID 33783966, 2021). "NLRP3 inflammasome is essential for defending against bacterial infections and mis regulated NLRP3 inflammasome has been implicated in metabolic inflammatory disorders including type 2 diabetes, atherosclerosis, heart reperfusion injuries, and chronic kidney diseases." (PMID 32668602, 2020). "Among those types of inflammasomes, NOD-like receptor pyrin domain containing 3 (NLRP3) possesses a critical role in inflammatory response, and associated with many diseases, including AD, Parkinson's disease, diabetes, atherosclerosis, and cerebral ischemia/reperfusion injuries." (PMID 32587516, 2020). "Among NLRPs, the NLRP3 (in humans encoded by the NLRP3 gene) is expressed predominantly in macrophages as a component of the inflammasome and is associated with many diseases, including gout, type 2 diabetes, multiple sclerosis, atherosclerosis, and neurological diseases and disorders." (PMID 33101293, 2020). "However, aberrant activation of the NLRP3 inflammasome is implicated in various diseases including diabetes, atherosclerosis, metabolic syndrome, cardiovascular, and neurodegenerative diseases; raising a tremendous clinical interest in exploring the potential inhibitors of NLRP3 inflammasome." (PMID 31749805, 2019). "However, the aberrant activation of the NLRP3 inflammasome has been linked with several inflammatory disorders, which include cryopyrin-associated periodic syndromes, Alzheimer’s disease, diabetes, and atherosclerosis." (PMID 31284572, 2019). "Anomalous NLRP3 inflammasome activation is linked with the development of many diseases, especially age-associated ailments for example various metabolic syndromes and metabolic disorders including gout, atherosclerosis, Alzheimer's disease (AD), and type II diabetes (T2D)." (PMID 31749805, 2019). "This is likely to explain why NLRP3 is activated by genetically-distinct programmed cell death pathways that all cause membrane damage, and importantly, may also account for why the diverse number of cellular stressors linked to atherosclerosis and diabetes all cause pathological NLRP3 activity." (PMID 29515457, 2018). "In the present study, we constructed lentiviral vectors to knock down NLRP3 to evaluate the role of the NLRP3 inflammasome in atherosclerosis in apolipoprotein (Apo) E-deficient mice, which can develop severe hypercholesterolemia and spontaneous atherosclerosis." (PMID 24999295, 2014).